VEGFA (vascular endothelial growth factor A)
Diseases named in the same sentence as VEGFA in open-access papers (continued):
Sharing a sentence is not in itself a finding about the gene and the disease.
Gorham syndrome (3 papers, 2015 to 2023). "Vascular endothelial growth factor-A (VEGF-A) was previously shown to be increased in Gorham’s syndrome, and Propranolol to be able to decrease VEGF-A levels." (PMID 26238450, 2015).
liver failure (3 papers, 2013 to 2021). A liver disease characterized by the liver losing or has lost all of its function. "HGF, IGF1 and VEGFA play central roles in protecting against hepatic damage under hepatic I/R conditions and some of these growth factors are being tested in clinical trials, for instance on patients with liver failure." (PMID 34444713, 2021).
meningeal tumors (3 papers, 2015 to 2024). "Intertumor heterogeneity in the aggressiveness of meningeal tumors reflected differences in angiogenic activity and expression of vascular endothelial growth factor A (VEGF-A) and interleukin 8 (IL-8)." (PMID 26667022, 2015).
microcephaly (3 papers, 2018 to 2023). A congenital or acquired developmental disorder in which the circumference of the head is smaller than normal for the person's age and sex. "In this study, we reported an interesting association of alleles and haplotypes of NOS2, VEGFA, and TNF genes with the CZS development and severity of the microcephaly in the CZS." (PMID 33672623, 2021).
polycystic kidney disease (3 papers, 2021 to 2024). A usually autosomal dominant and less frequently autosomal recessive genetic disorder characterized by the presence of numerous cysts in the kidneys leading to end-stage renal failure. "VEGFA is also implicated, except in DN, in polycystic kidney disease, suggesting that its role is significant for the maintenance of good functioning of the renal vascular system." (PMID 35008447, 2021).
psychosis (3 papers, 2018 to 2024). "To the best of our knowledge we are the first group to demonstrate that the VEGFA polymorphism, rs2146323, has a dimensional effect on psychosis membership." (PMID 30310054, 2018). "However, the influence of VEGFA gene variants on clinical and neuroimaging phenotypes in psychotic disorders has yet to be shown." (PMID 30310054, 2018). "In the present study, we examined whether different VEGFA gene variants influence psychosis risk, symptom severity, cognition, and brain volume." (PMID 30310054, 2018). "Vascular endothelial growth factor A (VEGFA) dysfunction may contribute to a number of pathological processes that characterize psychotic disorders." (PMID 30310054, 2018). "There are no human or animal studies evaluating the effects of VEGFA polymorphisms on psychotic or cognitive phenotypes in psychotic disorders." (PMID 30310054, 2018). "However, there are no studies to date examining the effects of these VEGFA polymorphisms on clinical and structural neuroimaging phenotypes in psychotic disorders." (PMID 30310054, 2018).
seminoma (3 papers, 2019 to 2022). A radiosensitive malignant germ cell tumor found in the testis (especially undescended), and extragonadal sites (anterior mediastinum and pineal gland). "Expression of VEGFA, a gene that has been associated with metastasis, was also increased in cocultured Tcam-2 cells, suggesting that T cells possibly increase the invasiveness of seminoma cells." (PMID 35269507, 2022). "Our finding that VEGFA mRNA levels are increased in Tcam-2 cells cocultured with T cells can thus be considered as a first hint that TIICs might increase the tendency of seminomas to metastasize." (PMID 35269507, 2022).
spinocerebellar ataxia type 1 (3 papers, 2020 to 2021). Spinocerebellar ataxia type 1 (SCA1) is a subtype of type I autosomal dominant cerebellar ataxia (ADCA type I) characterized by dysarthria, writing difficulties, limb ataxia, and commonly nystagmus and saccadic abnormalities. "Evidences were provided that increased miR-150 levels found in Purkinje neurons of the mouse model of spinocerebellar ataxia type 1 may modulate disease pathogenesis by targeting the expression of RGS8 and VEGFA genes." (PMID 32655365, 2020).
syphilis (3 papers, 2016 to 2025). A contagious bacterial infection caused by the spirochete Treponema pallidum. "Histological sections also showed significant increases in the expressions of Vascular Endothelial Growth Factor A(VEGFA) and ICAM‐1 in the derm‐mucosa of syphilis patients." (PMID 35274369, 2022).
type 2 diabetic nephropathy (3 papers, 2014 to 2024). "Numerous studies have demonstrated that serum VEGFA levels can effectively reflect the progression of type 2 diabetic nephropathy, with higher sensitivity and specificity observed in patients." (PMID 38275711, 2024). "In the same manner and in a rat model of type 2 diabetic nephropathy, Xu and colleagues demonstrated that Pioglitazone can significantly reduce the hyperactivation of VEGFA in kidneys." (PMID 33062917, 2020). "Consequently, VEGFA serves as a valuable biomarker for early diagnosis and monitoring therapeutic efficacy in type 2 diabetic nephropathy." (PMID 38275711, 2024).
urinary tract infection (3 papers, 2022 to 2025). "Moreover, genetic alterations of vascular endothelial growth factor A (VEGFA) and transforming growth factor beta 1 (TGFβ1) are related to kidney scarring and progressive kidney disease after urinary tract infections, especially those associated with vesicoureteral reflux." (PMID 37893554, 2023).
adenovirus infection (2 papers, 2016 to 2020). "A significant decrease in VEGFA expression was observed after adenovirus infection." (PMID 27528029, 2016).
angiokeratoma (2 papers, 2020 to 2024). A vascular lesion in the papillary dermis resulting from ectasia of pre-existing vessels. "Indeed, VEGFA was shown to be significantly high in FD patients and associated with other characteristic signs of the disease such as angiokeratomas, sweating abnormalities, and Fabry Facies." (PMID 38892211, 2024). "Of note, FGF2, IL-7 and VEGFA explained solely a small variance fraction of phenotype, sudation disorder, and angiokeratoma, respectively." (PMID 32370284, 2020).
brain inflammation (2 papers, 2015 to 2024). "Recently, astrocyte-derived VEGFA was reported to drive blood-brain barrier disruption (where astrocytes also retract their endfeet from vessels) in brain inflammatory disease and inhibition of VEGFA signaling suggested as a protective approach." (PMID 25750613, 2015).
choroideremia (2 papers, 2012 to 2021). Choroideremia (CHM) is an X-linked chorioretinal dystrophy characterized by progressive degeneration of the choroid, retinal pigment epithelium (RPE) and retina. "A more recent study further identified VEGFA as one of a group of factors that is frequently expressed in a variable manner in the monocytes of choroideremia patients, and its levels correlated with disease severity." (PMID 23166713, 2012).
CNS leukemia (2 papers, 2017 to 2022). "Expression of miR-181a, a VEGFA-regulating microRNA which showed increased level in CNS leukemia in our previous experiments, was then paralleled with VEGF-A concentration." (PMID 35449729, 2022). "Furthermore, elevated CSF levels of VEGFA have been identified in patients with CNS leukemia." (PMID 28491865, 2017). "Vascular endothelial growth factor A (VEGF-A) and microRNA-181a (miR-181a) concentrations measured in different sample types of patients with and without CNS leukemia." (PMID 35449729, 2022).
crescentic glomerulonephritis (2 papers, 2013 to 2017). A histopathologic term for a pattern of diseases characterized by extensive crescent formation in the glomeruli; patients present clinically with rapid deterioration of renal function, and possible progression to end-stage renal failure within weeks or months. "In crescentic glomerulonephritis JunD deficiency may cause increased oxidative stress in the glomerular podocytes, leading to altered VEGFA expression and subsequent glomerular injury." (PMID 23398888, 2013).
diabetic angiopathies (2 papers, 2019 to 2022). "Our results indicated that Nar exerted anti-proliferation and anti-migration effects on high-glucose-induced VSMCs through decreasing expression of the target protein VEGFA, and then downregulating the PI3K/Akt/CREB5 pathway, suggesting its potential for treating diabetic angiopathies." (PMID 35754483, 2022).
diffuse astrocytoma (2 papers, 2012 to 2020). A low-grade (WHO grade II) astrocytic neoplasm. "Interestingly, several of these differentially expressed genes identified in our study have also emerged as genes relevant for discriminating distinct subtypes of diffuse astrocytomas in other studies, including the GBM-associated CHI3L1, COL1A1, VEGFA and ANXA genes." (PMID 32647207, 2020).
endometritis (2 papers, 2024 to 2025). An acute or chronic, usually bacterial infectious process affecting the endometrium. "To further investigate the impact of CE on angiogenesis, we collected endometrial tissue samples from CE patients and mouse endometritis models.Immunohistochemical staining for the angiogenesis markers CD31, VEGFA, VEGFR2 was performed." (PMID 41408309, 2025).
eosinophilia (2 papers, 2020 to 2025). "More interestingly, inspired by two cases of THSD7A-associated MN accompanied by angiolymphoid hyperplasia with eosinophilia (ALHE), the researchers assumed that vascular endothelial growth factor A (VEGF-A) up-regulated the expression of THSD7A in endothelial cells in vitro." (PMID 33042109, 2020).
gallstones (2 papers, 2012 to 2018). Solid crystalline precipitates in the biliary tract, usually formed in the gallbladder, resulting in the condition of cholelithiasis. "Thus, the role of VEGFA in gallstones susceptibility could be attributed to the process of blood vascularization during acute and/or chronic inflammation; however, the functional effects of these variants are unknown." (PMID 23057767, 2012). "In addition, liver tissues from patients with NAFLD with gallstones had increased levels of HIF-1α, HMOX1, and VEGFA mRNAs, compared with livers from patients with NAFLD without gallstones." (PMID 29955245, 2018).
herpetic keratitis (2 papers, 2022 to 2023). "More recently, it was shown that in herpetic keratitis, both CD4+ T cells and myeloid cells secrete high levels of vascular endothelial growth factor-A, which is pathogenic to corneal nerves." (PMID 37217914, 2023).
myxoid liposarcoma (2 papers, 2008 to 2016). A liposarcoma characterized by the presence of round non-lipogenic primitive mesenchymal cells and small signet ring lipoblasts within a myxoid stoma with a branching vascular pattern. "Similar to our finding that FUS-CHOP promotes angiogenesis, we also demonstrated that eIF4E promotes the production of angiogenic factors in myxoid liposarcoma cell lines, as eIF4E siRNA knockdown significantly reduced the expression of VEGFA, VEGFB, and VEGFR3." (PMID 27822137, 2016). "The knockdown of FUS-CHOP in myxoid liposarcoma cells inhibited cell growth, induced cell cycle arrest, and reduced expression of VEGFR1 and the angiogenic ligand VEGFA." (PMID 27822137, 2016). "Similarly, pharmacologic inhibition of eIF4E by 4EGI-1 decreased the expression of VEGFR1, VEGFR3, VEGFA, and VEGFB in myxoid liposarcoma cell lines." (PMID 27822137, 2016).
Paget disease (2 papers, 2006 to 2020). A malignant neoplasm composed of large cells with large nuclei, prominent nucleoli, and abundant pale cytoplasm (Paget cells). "The VEGFA expression score tended to be higher in the Paget disease group (3.4 ± 1.9) than in the control group (2.1 ± 1.5, p = 0.104), but the difference was not statistically significant." (PMID 32527320, 2020). "In our results, because varying degrees of VEGF expression were observed in both Paget and non-Paget disease cells, the evaluation of VEGFA expression was difficult." (PMID 32527320, 2020). "In the present study, the VEGFA expression score tended to be higher in the Paget disease group than in the control group, although the difference was not statistically significant." (PMID 32527320, 2020). "In contrast, the relationship between VEGFA expression and Paget disease is controversial." (PMID 32527320, 2020).
Pasteurella multocida Infection (2 papers, 2023 to 2024). "Pasteurella multocida infection increases the permeability of the respiratory epithelial barrier and promotes the production of VEGFA in mouse infection models." (PMID 36916939, 2023).
Priapism (2 papers, 2018 to 2024). A painful and harmful medical condition in which the erect penis doesn't return to its flaccid state, despite the absence of both physical and psychological stimulation, within four hours. "A high AUC for VEGFA:Ang 2 and Ang 2:VEGFA ratios suggests a potential predictor for angiogenic imbalances in SCD, possibly linked to complications like priapism or leg ulcers." (PMID 39749215, 2024).
respiratory infection (2 papers, 2016 to 2023). "In agreement with the results of those studies, our findings indicate that respiratory infection induces respiratory epithelial permeability by activating HIF-1α–VEGFA signaling." (PMID 36916939, 2023).
Sinus bradycardia (2 papers, 2022 to 2024). Bradycardia related to a mean resting sinus rate of less than 50 beats per minute. "There are 54 targets of action in the treatment of sinus bradycardia, of which 19 targets such as AKT1, IL6, TNF, and VEGFA are the core targets of Datura metel in the treatment of sinus bradycardia." (PMID 36626429, 2022). "The results of the network screening of core targets showed that AKT1, IL6, VEGFA, and TNF were the top 4 core target proteins in terms of degree value, and maybe the most core targets for the treatment of sinus bradycardia with Yohimbe." (PMID 36626429, 2022).
Venous malformation (2 papers, 2021 to 2023). A vascular malformation resulting from a developmental error of venous tissue composed of dysmorphic channels lined by flattened endothelium and exhibiting slow turnover. "(C–E) Correlation between transforming growth factor A (TGFA) and HIF1A (C), HIF2A (D), and VEGFA (E) mRNA expression levels detected in angiomatosis of soft tissue (AST) and venous malformation (VM) lesions (n=23)." (PMID 37199488, 2023).
vesico-ureteral reflux (2 papers, 2022 to 2023). "Another notable fact is that polymorphisms involving vascular endothelial growth factor A (VEGFA) and transforming growth factor beta 1 (TGFβ1) were related to kidney scarring after UTIs and progressive kidney disease, especially associated with vesico-ureteral reflux." (PMID 36676673, 2022).
ampulla of vater cancer (1 paper, 2012). A primary or metastatic malignant neoplasm involving the ampulla of Vater. "We observed suggestive associations for SNPs in VEGFA with biliary stones, RNASEL with ampulla of Vater cancer, and IL8 with gallbladder and ampulla of Vater cancers after correcting for multiple comparisons (FDR≤0.2)." (PMID 23057767, 2012). "Suggestive associations were observed for SNPs in VEGFA with biliary stones, IL8 with gallbladder and ampulla of Vater cancers, and RNASEL with ampulla of Vater cancer (false discovery rate≤0.2)." (PMID 23057767, 2012).
ANCA-associated vasculitis (1 paper, 2025). "To further explore tissue-specific expression patterns, we validated the expression characteristics of the two oxidative stress-related hub genes (VCAM1 and VEGFA) identified from the tubulointerstitial dataset in ANCA-associated vasculitis glomerular tissues (GSE104948 and GSE108109)." (PMID 40369957, 2025).
autoimmune hepatitis (1 paper, 2022). Hepatitis caused by autoantibodies. "Thus, the key target genes for autoimmune hepatitis treatment mainly included AKT1, IL6, VEGFA, CASP3, JUN, MYC, etc.." (PMID 36558908, 2022).
breast hyperplasia (1 paper, 2025). Breast hyperplasia refers to hyperplastic proliferations of the epithelial cells in the breast parenchyma. "The expression of angiogenic factors (e.g., VEGFA, FGF2) is closely related to the occurrence and development of breast hyperplasia." (PMID 40550087, 2025).
cleft palate (1 paper, 2021). Cleft palate is a fissure type embryopathy that affects the soft and hard palate to varying degrees. "Moreover, some studies have also suggested that VEGFA 120/120 mice have craniofacial defects, including cleft palate and developmental disorders in mandibular." (PMID 33947308, 2021).
condyloma acuminatum (1 paper, 2024). "VEGFA and SerRS levels were measured by qRT‐PCR, Western blotting and immunohistochemistry in clinical tissues from condyloma acuminatum patients." (PMID 39351642, 2024).
cutaneous leishmaniasis (1 paper, 2022). Leishmaniasis affecting the skin. "In addition, cutaneous leishmaniasis is also characterized by vascular remodeling and lymphangiogenesis mediated by the vascular endothelial growth factor A (VEGF-A)/VEGF receptor 2 (VEGFR-2) signaling pathway that is essential for lesion resolution." (PMID 35651602, 2022).
Ecchymosis (1 paper, 2018). A purpuric lesion that is larger than 1 cm in diameter. "Consequently, the ecchymosis observed in the pericardial cavity or tail in seriously affected D. rerio embryos by overexpressing C. semilaevis Rspo3 may result from the downregulation of VEGFa." (PMID 29966290, 2018).
Fuchs’ dystrophy (1 paper, 2024). "The fact that VEGFA (angiogenic factor), βNGF (neurotrophic factor) and TGFβ1 (anti-inflammatory and profibrogenic factor) were upregulated in Fuchs’ dystrophy but not significantly linked to gender, is in line with previous studies." (PMID 38999352, 2024).
hepatopulmonary syndrome (1 paper, 2020). Hepatopulmonary syndrome (HPS) is a lung disease characterized by widening of arteries and veins (dilatation) in the lungs in people who have chronic liver disease. "In a rat model of hepatopulmonary syndrome, quercetin predominantly inhibited pulmonary vascular angiogenesis by regulate VEGFA/VEGFR-2 pathways." (PMID 33424592, 2020).
hip osteoarthritis (1 paper, 2025). "Further ligand-receptor interaction analyses showed that the VEGFA, VEGFB and CXCL8 associated interaction pairs were significant in the crosstalk between neutrophil and endothelium in hip osteoarthritis (HOA) group which may enhance the angiogenesis." (PMID 40169566, 2025).
HIV nephropathy (1 paper, 2020). "VEGFA up‐regulation has been observed in humans with HIV and in animal experimental models of HIV nephropathy and VEGFA inhibition has been proposed as a potential treatment." (PMID 33067928, 2020).
insomnia (1 paper, 2022). A sleep disorder characterized by difficulty in falling asleep and/or remaining asleep.
intraductal papillary mucinous neoplasms (1 paper, 2023). "Recently, it was observed that VEGFA spliced isoforms show different expression levels in normal pancreas, benign pancreatic serous cystic neoplasms, mucinous cystic neoplasms and intraductal papillary mucinous neoplasms." (PMID 37880792, 2023).
lentivirus infection (1 paper, 2023). Virus diseases caused by the Lentivirus genus. "To examine whether USP22 affected the histone H2Bub or ZEB1 recruitment to the VEGFA-promoter I region, we first constructed HCCLM3 cell lines with stable knockdown of USP22 (shUSP22) by lentivirus infection, a scramble shRNA as a control (shCtrl)." (PMID 36906615, 2023).
mammary Paget disease (1 paper, 2020). A malignant neoplasm in which there is infiltration of the skin overlying the breast by neoplastic large cells with abundant pale cytoplasm and large nuclei with prominent nucleoli (Paget cells). "Subsequently, we analyzed the relationships between these vascular parameters and angiogenic factors such as bFGF and VEGFA using immunohistochemistry to determine the mechanism of angiogenesis in mammary Paget disease." (PMID 32527320, 2020). "Therefore, angiogenesis in mammary Paget disease was promoted by bFGF predominantly, but VEGFA may cooperate with bFGF to achieve this effect." (PMID 32527320, 2020).